XBP1 (X-box binding protein 1)
Diseases named in the same sentence as XBP1 in open-access papers (continued):
Sharing a sentence is not in itself a finding about the gene and the disease.
tumor (continued). "Furthermore, under unfavorable conditions, such as hypoxia and lack of nutrients, cancer cells lead to the accumulation of unfolded proteins, which trigger the activation of ER stress and IRE-1α-XBP1 in TDCs (Tumor-associated dendritic cells), and then suppresses their antigen-presenting functions." (PMID 31121863, 2019). "Additionally, others have reported that lipid peroxidation by reactive oxygen species within tumor-associated DC yields byproducts that upregulate the ER stress sensor XBP1, which activates genes involved in the biosynthesis and accumulation of triglycerides known to be linked with DC dysfunction." (PMID 29209327, 2017). "Moreover, targeted deletion or inactivation of XBP-1 to quench the unfolded protein response to stress was demonstrated to restore the immunostimulatory activity of ID8DV tumor associated CD11c+ dendritic cells and promoted the development of antitumor CD8+ T cell populations." (PMID 27447180, 2016). "The increased Akt activation by lenalidomide treated XBP1-CTL during tumor recognition may be associated with costimulatory signaling molecule CD28, a critical regulator of T cell proliferation and important for T cell activation and effector cells development." (PMID 27668268, 2015). "In WT tumor cells, regulons associated with NFKB1, XBP1, JUN, SREBF2, and EHF exhibited elevated activity." (PMID 40767963, 2025). "Our results show that the components of the IRE1α/XBP1 arm of the UPR are significantly elevated in skeletal muscle of KPC tumor-bearing mice." (PMID 40655023, 2025). "Impairment of IRE1α-XBP1 has been reported in certain type of cancer cells and is thought to contribute to tumor growth." (PMID 40701245, 2025). "Results showed that KPC tumor-induced increase in the mRNA levels of Fbxo32, Trim63, Map1lc3b, Cd36, Acox3, and spliced-Xbp1 (sXbp1) in skeletal muscle were significantly reduced by treatment of mice with 4μ8C." (PMID 40655023, 2025). "Conversely, exogenous expression of spliced XBP1 can restore the tumor growth phenotype, underscoring the central regulatory role of this pathway in tumor progression." (PMID 41209558, 2025). "XBP1s, a transcriptionally active spliced form of XBP1, accelerates tumor progression by facilitating cell proliferation and G1/S transition, and attenuates the efficacy of palbociclib and fulvestrant." (PMID 40940685, 2025). "The mechanism of lipid peroxidation in tumor-associated DCs to the ER stress response is mediated by the inositol-requiring protein 1 (IRE-1) and its downstream target X-box binding protein 1 (XBP1)." (PMID 40709184, 2025). "Lipid peroxidation promotes the activation of X-box binding protein 1 (XBP-1), a key mediator of tumor activation." (PMID 40696413, 2025). "GNF-2, a c-Abl inhibitor, has shown anti-tumor effects in primary MM cells through IRE1/XBP1 activation." (PMID 40563622, 2025). "This XBP1-dependent disruption of dendritic cell antigen presentation functions inhibits local T cells’ anti-tumor responses." (PMID 41301006, 2025). "The role of the IRE1α/XBP1 signaling in the activation of IL-6-JAK-STAT signaling is also supported by the finding that myofiber-specific deletion of XBP1 strongly inhibited the phosphorylation of STAT3 in skeletal muscle of KPC tumor-bearing mice." (PMID 40655023, 2025). "The IRE1α/XBP1 axis is especially important for both tumor survival and immune regulation among the three UPR branches." (PMID 41350724, 2025). "For example, the IRE1α-XBP1 pathway has been shown to play a critical role in immune evasion by activating XBP1 in infiltrating dendritic cells within the tumor microenvironment." (PMID 41516218, 2025). "The endoplasmic reticulum stress (ER) response factor X-box binding protein 1 (XBP1) promotes endogenous tumor growth, and is also one of the by-products of lipid peroxidation." (PMID 40959280, 2025). "Skeletal muscle-specific deletion of the XBP1 transcription factor significantly attenuates tumor-induced muscle atrophy." (PMID 41249735, 2025).
tumor (continued). "In tumor settings, mechanisms such as unfolded protein accumulation in DCs trigger ER stress through the IRE1α-XBP1 signaling axis, ultimately impairing their antigen-presenting capacity." (PMID 41176596, 2025). "Upon analyzing RNA‐seq data from the TCGA database using the GEPIA, we observed that XBP1 expression was predominantly restricted to breast tissue and significantly upregulated in tumor samples." (PMID 40940685, 2025). "Altogether, these results suggest that the IRE1α/XBP1 arm of the UPR is activated in skeletal muscle of mice in response to KPC tumor growth." (PMID 40655023, 2025). "XBP1 can activate and induce triglyceride synthesis in DCs, leading to increased lipid synthesis and inhibition of the anti-tumor ability of DCs215." (PMID 40959280, 2025). "For example, in BCa, combination of XBP1 short hairpin RNA with doxorubicin can significantly inhibit tumor growth in xenograft models, highlighting the role of IRE1α-XBP1s signaling in mediating chemoresistance." (PMID 41372991, 2025). "XBP1 overexpression and splicing (sXBP1) was reported in the tumor tissues of patients with HCC, breast adenocarcinoma, melanoma, and glioblastoma." (PMID 40650182, 2025). "Baseline markers such as GRP78/BiP and the XBP1 splicing ratio estimate how much a tumor is already relying on chaperone buffering or IRE1 signaling; this helps choose which arm to target (PERK/IRE1/ATF6, ROS amplification, Ca2+ handling, or proteostasis)." (PMID 41476609, 2025). "XBP1 promotes tumor cell proliferation and metastasis by modulating immune responses, influencing cell growth and metabolism, and contributing to angiogenesis." (PMID 39170695, 2024). "The results showed that the expression of B4GALT1 and XBP1 was mainly enriched in the tumor region of EC." (PMID 38517922, 2024). "Taken together, tumorous IRE1α-XBP1 axis activates CD8+T cell-dependent anti-tumor immunity and mediates the tumor-suppressive role of HA15." (PMID 38291473, 2024). "XBP1 is a unique basic region leucine zipper (bZIP) transcription factor that not only promotes tumor cell proliferation but also participates in immune evasion, angiogenesis, hypoxia, invasion, and metastasis during tumorigenesis." (PMID 39439891, 2024). "Research has found that IRE1 α/KIRA8, an inhibitor of the XBP1 signalling pathway, can significantly inhibit tumour growth and has a better therapeutic effect when combined with PD‐1 antibodies." (PMID 38520212, 2024). "The miR-18a/low tumours had higher expression of the luminality-associated genes like ESR1, GATA3, FOXA1, XBP1 and TFF1 and a lower expression of the basality-associated genes such as KRT18, KRT17, FOXC1, ANLN, STIL and MIA (p < 0.05)." (PMID 38786043, 2024). "It was shown that accumulation of cholesterol by CD8+ T cells in the tumor-induced expression of the inhibitory receptors PD-1 and 2B4 and promoted T cell exhaustion in an XBP1-dependent manner." (PMID 39080273, 2024). "Other studies have shown that tumor DCs can accumulate lipid peroxides through XBP1, inducing endoplasmic reticulum stress and inhibiting their antigen-presenting ability, thereby promoting tumor immune escape." (PMID 39769177, 2024). "Recent studies show that activation of the IRE1α/XBP1 pathway in tumor cells promotes tumor growth by enhancing cholesterol synthesis and secretion, while suppressing anti-tumor immunity." (PMID 39777330, 2024). "Studies in TNBC implicate XBP1-spliced (sXBP1) in promoting tumor vascularization and progression, and the XBP1 gene signature is predictive of the survival of patients with TNBC." (PMID 38969867, 2024). "Subsequently, tumorous IRE1α facilitated the expression and secretion of multiple chemokines and cytokines via XBP1-NF-κB axis, leading to increased infiltration and anti-tumor capacity of CD8+T cells." (PMID 38291473, 2024). "Tumorous IRE1α facilitates CD8+T cells-dependent anti-tumor immunity and improves immunotherapy efficacy by regulating chemokines and cytokines via XBP1-NF-κB axis." (PMID 38291473, 2024).
tumor (continued). "XBP1 also showed strong positive correlations with CD38 in 2 other patient tumor gene expression data sets." (PMID 40453054, 2024). "ASCs in tumour tissues with NACT expressed the highest levels of XBP1 and IGHG1 among the three tissue source types and the proportion of XBP1‐positive cells was the largest in tumour tissues with NACT among the three tissue source types." (PMID 36650114, 2023). "Our results revealed that the levels of GRP78, ATF4, CHOP, p‐IRE, and XBP1 expression were increased in mouse tumour tissue overexpressing USP19, indicating an increased ER stress parallel to the expression of USP19 in TNBC tumorigenesis." (PMID 37700495, 2023). "Having demonstrated increased UPR signaling in HKP1 tumor cells compared to normal lung resident epithelial cells in vivo, we analyzed the status of IRE1α-XBP1 signaling." (PMID 36624093, 2023). "As expected, relative to vehicle controls, there was strong activation of IRE1α-XBP1 in mCherry+ tumor cells sorted from HKP1 tumors, comparable to HKP1 cells experiencing thapsigargin (Tg)-induced ER stress in vitro." (PMID 36624093, 2023). "XBP1 knockdown effectively repressed tumour cell repopulation mediated by cytotoxic treatment in vitro and in vivo." (PMID 36639835, 2023). "XBP-1 co-localizes with hypoxia markers in tumors and the loss of XBP-1 increases the sensitivity of tumor cells to hypoxia-induced apoptosis and inhibits tumor growth, implicating XBP-1(S) as a critical survival factor under hypoxia." (PMID 36831485, 2023). "The level of total XBP1, that is, both XBP1s and unspliced form of XBP1 (XBP1u), was higher in tumor-infiltrating T cells and T cells cultured in TM or DM." (PMID 37147330, 2023). "The analysis showed the higher expression of XBP1 in tumour tissues as compared to tumour adjacent and healthy tissues (SF 2)." (PMID 36997866, 2023). "High levels of XBP1 in tumor-infiltrating dendritic cells can boost tumor growth and invasion by suppressing tumor immunity." (PMID 37189138, 2023). "AGR2 was slightly more highly expressed in HCC tumor tissues than in normal tissues, and the spliced XBP1 (XBP1 s) level was slightly more highly expressed in HCC tissues." (PMID 36899352, 2023). "We suggest that the correlation between AGR2 and XBP1 needs to be further demonstrated in more clinical specimens in the future (Normal: lanes 1–9, Tumor: lanes 1–5)." (PMID 36899352, 2023). "Possibly, early and constitutive overexpression of mPEGS1 in IRE1αKO tumor cell overrides the exquisite control exerted by the ER stress response mediated by the IRE1a-XBP1 pathway." (PMID 36624093, 2023). "Here, we further demonstrated that XBP-1(S) enhances the repression of the tumor-suppressive miR-34a by HIF-1A." (PMID 36831485, 2023). "Next, we assessed XBP1 expression in tumour tissues as compared to tumour adjacent and healthy tissues using GTEx and TCGA dataset (bc-GenExMiner v4.8)." (PMID 36997866, 2023). "Further analysis revealed a significant correlation between XBP1 splicing rate and various clinicopathological features of patients, including positive progesterone receptor status and larger tumor size (p < 0.05)." (PMID 37706018, 2023). "XBP-1(S) activation and the subsequent increase in protein folding capacities represent a central facilitator of tumor cell growth and tumor expansion/migration." (PMID 36831485, 2023). "Knockdown of XBP1 reduces the growth of cancer cells under a hypoxic environment and diminishes their ability to form tumours in NOD SCID mice." (PMID 38203358, 2023). "As the most conserved signaling pathway in the UPR, IRE1α participates in the regulation of various stages of tumor development, and XBP1 plays an irreplaceable role in promoting cell survival and tumor MDR." (PMID 37790807, 2023). "ER stress-induced miR-153 expression in breast cancer cells activates IRE1α and XBP1, which inhibits HIF1α expression and tumor angiogenesis by decreasing VEGFA production." (PMID 36890838, 2023).
tumor (continued). "In the context of a tumor microenvironment, hypoxia enhances XBP1 activation, and active XBP1s interact with HIF-1 to augment and encourage the transactivation of HIF1 target genes that progress cancer." (PMID 37904441, 2023). "We measured IRE1 RNase activity in tumor cDC1s from XBP1ΔDC and XBP1ΔDCIRE1truncDC mice by analyzing the expression of Xbp1 spliced and unspliced mRNA." (PMID 37346037, 2023). "It was recently shown that tumor associated DCs (tDCs) exhibit ER stress and increased IRE/XBP1 activation, resulting in reduced antitumor activity." (PMID 37395796, 2023). "It has been documented that XBP1 can regulate cholesterol biosynthesis in tumor cells, which can then be released into the tumor microenvironment to activate MDSCs." (PMID 37067519, 2023). "Apart from the direct effect on tumor cell survival, SIRT7 up-regulation also repressed anti-tumor immunity by promoting PD-L1 expression via the IRE1α-XBP1 axis." (PMID 36918544, 2023). "IRE1A and XBP-1 are central components of the unfolded protein response that is activated by ER stress, which is also induced in tumor cells as a response to harsh conditions surrounding tumors such as hypoxia and a limited supply of nutrients." (PMID 36831485, 2023). "In general, these studies show the prominent role of XBP1 in promoting tumor cell proliferation and reveal the regulatory mechanism of XBP1 at the transcriptional and post-translational levels." (PMID 35269888, 2022). "For further validation, we also detected the expression of XBP1 in clinical BC samples, the XBP1 expression levels were significantly higher in luminal BC tissues and lower in basal-like BC tissues than that in tumour adjacent tissues." (PMID 35543228, 2022). "In this regulation, XBP1-s binds to the TAp73 promoter and suppresses its transcriptional activity, leading to the enhanced proliferation of tumor cells." (PMID 35269888, 2022). "Compared with low-XBP1 group, BC patients in the high-XBP1 group had lower levels of immune-related gene sets, lower tumour purity and higher immune scores and higher stromal scores." (PMID 35543228, 2022). "As expected, representative mIHC images confirmed varying expression levels of PD1+CD8+ T cells and XBP1+CD8+ T cells in these iCCA tumor tissues." (PMID 35982235, 2022). "XBP1 aggravates hypoxia-inducible factor 1α (HIF1α) and activates its downstream pathways, leading to tumor angiogenesis and increased energy supply to support tumor progression and recurrence." (PMID 35884393, 2022). "We further investigated the role of XBP1 in immune characteristics, XBP1 was negatively correlated with the infiltration level of tumour-infiltrating immune cells (TILs) in BC across human cancers." (PMID 35543228, 2022). "In cancer, the IRE1α-XBP1 pathway can active DCs of the tumor microenvironment and regulates antitumor immunity to evade immune control." (PMID 35958574, 2022). "The ER stress sensor IRE1α and its substrate XBP1 in NK cells are elevated to boost anti-tumor effects through their downstream target c-Myc." (PMID 35884393, 2022). "Earlier reports indicate that XBP1 promotes tumor growth by regulating the properties of dendritic cells." (PMID 35910793, 2022). "The IRE1α–XBP1 pathway was found to mediate IL-6 expression and subsequently support tumor cell proliferation in HCC." (PMID 35203283, 2022). "XBP1 can regulate tumor cell proliferation by suppressing tumor suppressor genes as well as by activating oncogenes." (PMID 35269888, 2022). "IRE1α and its substrate XBP1 drive NK cells response to viral infection and in vivo tumor, as well as being critical for the proliferation of activated mouse and human NK cells." (PMID 35958574, 2022).
tumor (continued). "XBP1, an important factor mediating immunogenic chemotherapy, can exert anti-tumor immunity by regulating T cell function and dendritic cell homeostasis." (PMID 35991556, 2022). "The 3,6-DMAD-mediated inhibition of XBP1 splicing was cytotoxic to MM cell lines in vitro, and it affected the growth of MM tumor xenografts." (PMID 35626128, 2022). "Adaptation to tumor microenvironments such as hypoxia is crucial for increasing tumor cell survival and promoting tumor cell proliferation, and XBP1 is indeed involved in this regulation." (PMID 35269888, 2022). "When XBP1 is deleted, DCs regain their function to stimulate T cells and induce type 1 anti-tumor immune responses." (PMID 35062950, 2022). "Studies have shown that ER stress plays a crucial role in activation of hepatic stellate cells and that blocking the IRE1α–XBP1 pathway can significantly reduce liver fibrosis and tumor burden in several animal models for cirrhosis and HCC." (PMID 35203283, 2022). "XBP1-u then recruits FoxO1 to the 20S proteasome and degrades FoxO1 to inhibit autophagy, thereby suppressing tumor cell death." (PMID 35269888, 2022). "The GEPIA2 online tool was used to determine the differential expression of XBP1 in tumor tissues and adjacent peritumor normal tissues." (PMID 36092910, 2022). "In line with this, preclinical findings have demonstrated that experimental ablation of the key proteins of the UPR (PERK, IRE1 and XBP1) results in impaired tumor growth." (PMID 36139473, 2022). "STF-083010, which suppresses XBP1 splicing by blocking the activity of IRE1α, can increase the sensitivity of tumor cells to bortezomib and tamoxifen." (PMID 35269888, 2022). "The treatment with each checkpoint inhibitor also increased anti-tumor activities of XBP1/CD138/CS1-CTL against MM cells, evidenced by increased CD107a degranulation and IFN-γ production, with the highest anti-tumor activities induced by anti-LAG3 treatment." (PMID 34290359, 2022). "ERN1 is a transmembrane serine/threonine protein kinase for endoplasmic reticulum hemostasis, and its downstream target XBP1 is activated for tumor growth." (PMID 36139553, 2022). "Taken together, these studies directly suggested that XBP1 is an essential survival factor for hypoxic stress and tumor growth." (PMID 35402506, 2022). "Deletion of XBP1 altered the cytokine expression signature and promoted macrophage phagocytosis of tumor cells by disrupting self-recognition." (PMID 34667145, 2021). "In this study, we measured the expression level of XBP1 in 104 NSCLC tumor tissues and matched adjacent normal lung tissues (ANLTs) using immunohistochemical (IHC)." (PMID 34094948, 2021). "A high level of XBP1 in primary and metastatic breast tumors is correlated with tumor stage and poor prognosis of patients." (PMID 33746610, 2021). "AAV2-sgXbp1, which conditionally deletes XBP1 in TAMs, dramatically inhibited tumor formation in AOM-DSS mouse model." (PMID 34667145, 2021). "Depletion of XBP1 induces apoptosis and inhibits tumor growth in other cell lines via various mechanisms." (PMID 34121978, 2021). "All these data indicate an oncogenic role for XBP1, though evidence shows a tumor-suppressor function of RIDD activity." (PMID 33842465, 2021). "XBP-1-HIF-1a complex represents a crucial role in tumor growth and relapse by regulating genes involved in angiogenesis and metabolism such as VEGF, glucose transporter 1 (GLUT1), or pyruvate dehydrogenase kinase 1 (PDK1)." (PMID 34011277, 2021). "XBP1 depletion in TAMs changed the cytokine expression patterns and disrupted the self-recognition capacity of TAMs, thereby enhancing the anti-tumor activity of macrophages, which led to the inhibition of tumor progression." (PMID 34667145, 2021). "The UPR responds to ER stress resulting from the damaging accumulation of misfolded proteins, and XBP1 is important for tumour survival under stressful conditions like hypoxia." (PMID 34943783, 2021).